UBTD2 (ubiquitin domain containing 2)
Synonyms: DC-UbP; DCUBP; MGC30022
Tractability: PROTAC: ubiquitination databases record sites on it; its protein half-life has been measured.
Gene: Protein-coding gene on chromosome 5 (172,209,645 to 172,284,077, reverse strand). Ensembl gene ENSG00000168246.
Subcellular location: Cytoplasm
Gene Ontology:
Molecular function: protein binding
Cellular component: cytoplasm
Genetic constraint (gnomAD): Loss-of-function variants: 9 observed, 19.24 expected, observed/expected ratio (o/e) 0.47, 90% interval 0.28 to 0.82. The upper end of that interval is the gene's LOEUF score, 0.82, which puts it in group 3 of 6, group 1 being the genes least tolerant of losing a copy. Missense variants: 250 observed, 299.19 expected, observed/expected ratio (o/e) 0.84, 90% interval 0.75 to 0.93. Synonymous variants: 98 observed, 101.34 expected, observed/expected ratio (o/e) 0.97, 90% interval 0.82 to 1.14.
Homologues: Orthologues: chimpanzee UBTD2 (100% identical), macaque UBTD2 (100% identical), dog UBTD2 (98% identical), mouse Ubtd2 (97% identical), rat Ubtd2 (97% identical), rabbit UBTD2 (95% identical), pig UBTD2 (89% identical), guinea pig UBTD2 (88% identical), tropical clawed frog ubtd2 (87% identical), zebrafish ubtd2 (85% identical), Drosophila melanogaster CG1172 (51% identical). Paralogues in human: UBTD1 (63% identical).
Diseases named in the same sentence as UBTD2 in open-access papers:
UBTD2 is named in the same sentence as 3 diseases in open-access papers, as found by Europe PMC text mining. Sharing a sentence is not in itself a finding about the gene and the disease.
UBTD2 shares sentences with these, for which no sentence is quoted: Alzheimer disease (1 paper); frontotemporal dementia (1); neoplasm (1).